RN7SL130P (RNA, 7SL, cytoplasmic 130, pseudogene)
Gene: Miscellaneous RNA gene on chromosome 1 (63,655,743 to 63,656,047, forward strand). Ensembl gene ENSG00000244256.
Homologues: Orthologues: chimpanzee Metazoa_SRP (96% identical), macaque Metazoa_SRP (89% identical). Paralogues in human: RN7SL1 (82% identical), RN7SL2 (82% identical), RN7SL3 (81% identical), RN7SL126P (80% identical), RN7SL856P (79% identical), RN7SL45P (79% identical), RN7SL650P (79% identical), RN7SL321P (78% identical), RN7SL448P (78% identical), RN7SL709P (78% identical), RN7SL220P (78% identical), RN7SL320P (78% identical), and 704 more.